TSLP (thymic stromal lymphopoietin)
Diseases named in the same sentence as TSLP in open-access papers (continued):
Sharing a sentence is not in itself a finding about the gene and the disease.
asthma (continued). "The bronchial epithelium integrates complex inflammatory and remodeling processes in asthma by releasing IL-25, IL-33, and thymic stromal lymphopoietin (TSLP)." (PMID 37635231, 2023). "Several cytokines, including interleukin (IL)-4, IL-5, IL-13, IL-25, and IL-33, thymic stromal lymphopoietin (TSLP), and cells such as innate lymphoid cells type 2 (ILC2s), play crucial roles in orchestrating the inflammatory response in asthma." (PMID 37765327, 2023). "Epithelium-derived cytokines, including interleukin (IL)-25, IL-33, and thymic stromal lymphopoietin (TSLP), are major immune mediators secreted by epithelial cells that contribute to type 2 immune responses and the development of asthma." (PMID 36674744, 2023). "IL-25, IL-33, and TSLP were identified as the principal regulators of type 2 immunity in patients with allergic disease and asthma in recent years." (PMID 36674744, 2023). "What is more, both TSLP and IL-13 are co-expressed in the lung epithelial tissues of severe asthma patients." (PMID 37334374, 2023). "In a mouse model of asthma, anti-TSLP antibodies were found to effectively inhibit airway hyperresponsiveness in mice treated with EETs." (PMID 37752512, 2023). "In human studies, TSLP expression in the airway epithelium and lamina propria was increased in patients with severe asthma." (PMID 37371472, 2023). "Several cytokines have been involved in Th2-asthma, among them, the alarmins, initiators of T2 inflammation: IL-33, IL-25, and thymic stromal lymphopoietin (TSLP)." (PMID 36694181, 2023). "Biologic agents targeting inflammatory cytokines, comprising anti-immunoglobulin (Ig)E and anti-interleukin (IL)-4/IL-13, IL-5, IL-5R, and thymic stromal lymphopoietin (TSLP) have emerged as promising treatment options for patients with severe asthma." (PMID 36845128, 2023). "In patients with asthma, TSLP levels are related to airway obstruction, disease severity, and glucocorticoid resistance." (PMID 36601189, 2023). "SA ILC2s demonstrated a 100‐fold increased release of IL‐6 following stimulation with IL‐2, IL‐33, IL‐25 and TSLP compared to mild asthma and the controls." (PMID 37114915, 2023). "Our results show a positive correlation between nasal TSLP detection in severe bronchiolitis and the presence of current asthma, prescription of asthma maintenance treatment and respiratory admissions up to the age of 4 years." (PMID 36694181, 2023). "We investigated the effect of BT on the epithelial expression of the trio of alarmins IL-25 and IL-33 and TSLP which are well documented in asthma as well as on hBD2, an antimicrobial peptide." (PMID 37996952, 2023). "Tezepelumab, a human IgG2 monoclonal antibody that blocks human TSLP, was effective at reducing the rates of asthma exacerbations in patients with moderate to severe disease requiring long-acting beta-antagonists (LABAs) and medium to high doses of ICSs." (PMID 36674744, 2023). "Several biological agents, including anti-immunoglobulin E, anti-interleukin-5, and anti-thymic stromal lymphopoietin/interleukin-4, have been approved for the treatment of severe asthma." (PMID 38203353, 2023). "Recent work has highlighted the role of TSLP in various inflammatory diseases, which is an IL-7-like cytokine initiating and promoting type-2 inflammation, including AD, allergic rhinitis, and asthma." (PMID 38053996, 2023). "Tezepelumab (AMG 157, MEDI 9929) was the first anti-TSLP mAb to be approved by the US FDA for asthma treatment." (PMID 37334374, 2023). "Mediators, which are derived from epithelial cells of the airways (AECs), include cytokine alarmins such as IL-25, IL-33, and thymic stromal lymphopoietin (TSLP), which have arisen as crucial elements in the pathogenesis of asthma." (PMID 37685567, 2023). "Biologics targeting IgE, IL-4, IL-5, IL-13, and TSLP are used for uncontrolled severe asthma; their targets are all mediators produced by cells in the microenvironment of ILC2s." (PMID 36941691, 2023).
asthma (continued). "The epithelium-derived cytokines interleukin (IL)-25, IL-33, and thymic stromal lymphopoietin (TSLP) are important mediators that initiate innate type 2 immune responses in asthma." (PMID 36674744, 2023). "The researchers found that DEP-induced IL-25, IL-33, and TSLP expression was increased in primary bronchial epithelial cells from patients with mild asthma through the aryl hydrocarbon receptor and increased levels of acetyl-histone H3." (PMID 36674744, 2023). "Levels of both TSLP mRNA and protein are increased within the airway epithelium and submucosa in asthma compared with healthy controls." (PMID 37628907, 2023). "In severe asthma, TSLP is a key epithelial cytokine positioned at the top of the inflammatory cascade." (PMID 37628907, 2023). "Ecleralimab (CSJ117), a novel anti-TSLP monoclonal antibody fragment administered by inhalation, recently showed results from a phase I randomized controlled trial in mild asthma." (PMID 37377958, 2023). "Particularly, because the anti-TSLP antibody tezepelumab showed promise in patients with severe uncontrolled asthma, biologic agents targeting the alarmins have become of increasing interest." (PMID 36979498, 2023). "Our previous study showed that CpG-ODN administration alleviates the Th2/Th17 type inflammatory response to smoke-related asthma by inhibiting the TSLP-DC pathway." (PMID 36834541, 2023). "TSLP and IL-13 are attractive targets for asthma therapeutics due to their importance in asthmatic cellular signalling and overlap of the signalling effects of both cytokines." (PMID 37334374, 2023). "More recently, TSLP has emerged as an important factor in the pathogenesis of asthma, and increased levels of TSLP have been detected in asthma patients." (PMID 37063828, 2023). "Thymic stromal lymphopoietin (TSLP) is a pleiotropic cytokine that has emerged as a critical player in the development and progression of allergy and asthma." (PMID 37628907, 2023). "Of particular note, the recent approval of tezepelumab (anti-TSLP antibody) to treat asthma in humans provides the possibility to translate our mouse studies to human melanoma." (PMID 36107619, 2022). "Mechanistic studies indicate that TSLP drives eosinophilic inflammation and structural changes of the airway in asthma through actions on a wide variety of adaptive and innate immune cells and structural cells." (PMID 36245744, 2022). "Therefore, NETs could contribute to asthma pathobiology and exacerbations through the loss of integrity of the bronchial epithelium and the release of “upstream cytokines’’ such as alarmins (e.g., TSLP, IL-33)." (PMID 36359917, 2022). "Meanwhile, multiple studies suggest that ciliated cells are a source of cytokines, such as IL33 and TSLP, in asthma." (PMID 35627266, 2022). "All children with high TSLP BAL levels (n = 9) were classified as severe asthma and had significantly elevated levels of IL-5 (median values in pg/mL, 0.403 vs. 1.95, p = 0.01)." (PMID 36245744, 2022). "The newest treatment options for severe uncontrolled asthma include the mAbs anti-IL-4/IL-13 dupilumab and the anti-thymic stromal lymphopoietin (TSLP) tezepelumab." (PMID 36140430, 2022). "The inflammatory cytokines involved in the T2 type of asthma are mainly interleukin (IL) 5, 4, and 13, accompanied by those defined as alarmins, respectively IL-33, IL-25, and thymic stromal lymphopoietin (TSLP)." (PMID 36300189, 2022). "TSLP, a Th2-like cytokine, plays an important role in the pathogenesis of asthma, allergies, and other airway diseases." (PMID 35292112, 2022). "Studies using airway specimens derived from adults with asthma have confirmed that type 2 pro-asthmatic cytokines, such as Thymic Stromal Lymphopoietin (TSLP), are key mediators in the pathogenesis of the disease." (PMID 36245744, 2022). "The exhaled breath condensate levels of TSLP are significantly higher in patients with asthma than in controls." (PMID 35292112, 2022).
asthma (continued). "As a result, TSLP is now considered a promising biomarker and therapeutic target to improve outcomes for adults with uncontrolled severe asthma." (PMID 36245744, 2022). "The anti-thymic stromal lymphopoietin antibody (tezepelumab) has therapeutical potential for inadequately controlled asthma." (PMID 35269440, 2022). "TSLP expression is increased in the airways of asthma patients compared to healthy individuals and correlates with disease severity and lung function." (PMID 35572064, 2022). "In support of these efforts, observations from the NAVIGATOR trial imply that targeting TSLP in patients with tezepelumab results in reduced asthma exacerbations, improved lung function and control of the disease." (PMID 36311787, 2022). "IL-25, IL-33 and TSLP are the type alarmins cytokine and released mainly by asthma airway epithelial cells." (PMID 35351157, 2022). "The complex pathogenesis of asthma and AD were better clarified in recent years, thus suggesting novel therapeutical strategies, such as anti-TSLP (tezepelumab) and anti-IL-4 (dupilumab) antibodies, respectively." (PMID 36364420, 2022). "We also studied epithelial-cell-derived IL-33, IL-25, and TSLP, which were regarded as alarmins and played pivotal roles in the initiation of allergic inflammation in asthma." (PMID 35983066, 2022). "Relevant to the present review is the consideration of potential predictors of good asthma response among anti-IgE, anti-IL-5, anti-IL-4R and anti-TSLP therapy, if locally accessible and cost-effective." (PMID 35743783, 2022). "Understanding the possible mechanisms of the effect of TSLP on ROS production can help us identify targets for therapy or find novel pharmaceutical strategies to reduce asthma morbidity." (PMID 35292112, 2022). "Epithelial-derived alarmins (IL-33, TSLP, and IL-25) play an upstream role in the pathogenesis of asthma." (PMID 35693823, 2022). "Thymic stromal lymphopoietin (TSLP) is increasingly recognized as a key molecule in asthma pathogenesis and as a promising therapeutic target in adults." (PMID 36245744, 2022). "Epithelial cell-derived mediators including the alarmin cytokines IL-25, IL-33, and thymic stromal lymphopoietin (TSLP) have emerged as key players in propagating asthma pathogenesis." (PMID 35406669, 2022). "Our team has previously reported that significant airway secretion of TSLP occurs during viral respiratory infections in young children particularly in those who have recurrent wheezing illnesses or have been diagnosed with asthma." (PMID 36245744, 2022). "Collectively, it is evident that from their prime position in the inflammatory cascade, TSLP, IL-25 and IL-33 orchestrate the elicitation and activity of multiple effector cells and pathways that constitute the asthma phenotype." (PMID 36311787, 2022). "Epithelial-derived cytokines [i.e., TSLP, IL-33, IL-25] act as upstream cytokines in asthma pathobiology." (PMID 36359917, 2022). "In the study of asthma, it was also observed that after inhibiting the TSLP-DC-OX40L signaling pathway, the secretion of Th2 cells and factors decreased, which played a therapeutic role." (PMID 36172190, 2022). "Studies have shown that IL-33 and TSLP modulate migration of CD34+ progenitor cells in patients with asthma, further enhancing eosinophilia and basophilia, and also inversely correlate with lung function." (PMID 36311787, 2022). "Our results are the first to demonstrate that, during baseline bronchoscopic evaluation, the most severe pediatric asthma cases have higher TSLP protein levels in the lungs." (PMID 36245744, 2022). "Murine models have provided further evidence for the role of TSLP in airway inflammation and asthma." (PMID 36245744, 2022). "Future studies are needed to further characterize pediatric severe asthma based on high TSLP levels to define best potential candidates for emerging anti-TSLP targeted therapies." (PMID 36245744, 2022).
asthma (continued). "It is commonly thought that epithelial-derived alarmins (IL-33, TSLP, IL-25) play an upstream role in the pathogenesis of asthma where basophil-derived cytokines are a pivotal component of allergic inflammation." (PMID 35693823, 2022). "Understanding how TSLP secretion is related to asthma severity and type 2 lower immune responses in children is needed to develop new targeted treatments for this age group." (PMID 36245744, 2022). "In our current study we also found that children with asthma and high pulmonary TSLP levels have greater lower airway obstruction (reduced FEV1/FVC ratios)." (PMID 36245744, 2022). "Five genes previously reported in a genome-wide association study (GWAS) on asthma, including TSLP, SLC9A4, PSMB8, IGSF5, and IKZF4 were demonstrated association in the asthma vs. control analysis." (PMID 35524249, 2022). "Thymic Stromal Lymphopoietin (TSLP) and Th2 immunity have been extensively studies in the context of atopic diseases like asthma and atopic dermatitis." (PMID 36467403, 2022). "In asthma, the number of cells expressing TSLP messenger ribonucleic acid (mRNA) within the airway epithelium and submucosa is markedly increased compared to healthy controls." (PMID 36140430, 2022). "The results show that the amount of TSLP in the BALF by OVA stimulation was increased 1.7 times in the asthma induction group (73.9 ± 7.5 pg/mL) compared to the normal group (41.7 ± 0.4 pg/mL)." (PMID 36115955, 2022). "Allergens, toxic substances, and viral infections cause the release of IL-25, IL-33, TSLP cytokines, the so-called alarmins, from the airway epithelium and induce type-2 inflammation via ILC2 and Th2 cells in asthma." (PMID 36326393, 2022). "IL‐5, CCL17, CCL26 and TSLP concentrations were elevated significantly in asthma overall compared with health." (PMID 35579040, 2022). "In endobronchial biopsies from prednisone-treated patients with severe asthma, ILC2s were colocalized in TSLP-immunopositive regions." (PMID 35572064, 2022). "ROS can lead to direct oxidative damage and cell abscission of bronchial epithelial cells in asthma, which activates epithelial cells and releases cytokines such as IL-25, IL-33, and thymic stromal lymphopoietin (TSLP)." (PMID 35419163, 2022). "Both TSLP and ROS production are important for the pathogenesis of asthma and other allergic diseases." (PMID 35292112, 2022). "Taken together, these studies will provide much needed information on the benefits of TSLP blockade in asthma." (PMID 35572064, 2022). "Pediatric subjects with severe asthma had greater TSLP BAL levels at baseline relative to mild or moderate asthmatic subjects (p = 0.016)." (PMID 36245744, 2022). "TSLP expression is significantly increased in asthma patients compared to healthy individuals in the inner and outer epithelial layers of airway biopsies as well as in serum samples, sputum, exhaled breath condensate, and bronchoalveolar lavage fluid." (PMID 35572064, 2022). "Allergen sensitization developed through the barrier-defective skin of AD has been recognized to be a critical step leading to asthma, in which thymic stromal lymphopoietin (TSLP) was previously shown to be critical." (PMID 36050303, 2022). "The current therapeutic approach for Th2-high severe asthma is based on biologics targeting allergy molecules (IgE) and eosinophilic interleukins (IL-5, IL-4, IL-13, TSLP)." (PMID 35887589, 2022). "Randomized controlled clinical trials have demonstrated benefit when blockade of TSLP and IL-33 were added to standard of care medications, suggesting these are important new targets for treatment of asthma." (PMID 35406669, 2022). "TSLP's involvement in asthma also appears to extend beyond TH2 polarization of the type of response." (PMID 36245744, 2022). "Airway epithelial cells produce IL-33, IL-25, and thymic stromal lymphopoietin (TSLP) under allergen stimulation in the type 2 immune reaction of asthma." (PMID 36578010, 2022).
asthma (continued). "In models of asthma and parasitic infections, blocking any of IL-25, IL-33, or TSLP alone showed only modest results, while combinatorial targeting of IL-33, IL-25 and TSLP significantly reduced collagen expression and fibrosis." (PMID 38566909, 2022). "We compared lung function in children with asthma based on presence of high pulmonary TSLP levels >75th percentile." (PMID 36245744, 2022). "Airway epithelial cells (AECs) from humans with asthma have increased TSLP mRNA levels, and over-expression of TSLP induces experimental asthma in mice." (PMID 36685501, 2022). "Other therapeutic targets for both AD and asthma are the alarmins TSLP and IL-33, released from barrier tissues which activate the innate immune response." (PMID 35743678, 2022). "Therapies targeting mast cell mediators and/or their receptors, including monoclonal antibodies targeting IgE, IL-4/IL-13, IL-5/IL-5Rα, IL-4Rα, TSLP, and IL-33, have been found safe and effective in the treatment of different phenotypes of asthma." (PMID 36430941, 2022). "Due to TSLP’s role in driving Type 2 inflammation, clinical studies have been investigating the monoclonal antibody targeting TSLP (tezepelumab) in asthma and atopic dermatitis." (PMID 36289748, 2022). "This fundamental knowledge has led to the discovery of novel anti-TSLP asthma therapies (Tezepelumab) for adults." (PMID 36245744, 2022). "TSLP production seem to be increased in chronic inflammatory diseases of the airways (asthma, CRS) and skin (atopic dermatitis)." (PMID 35572064, 2022). "Tezepelumab is a humanized IgG2λ mAb that inhibits thymic stromal lymphopoietin (TSLP), an airway epithelial cytokine, and it has shown a wider therapeutic action in both type 2 high and low severe asthma patients." (PMID 35743783, 2022). "Consistently, we detected IL-4, IL-5, IL-13, IL-25, IL-10, IL-33, and TSLP in induced sputum of asthma and proved a positive correlation between BIRC3 and these cytokines." (PMID 35287655, 2022). "DupixentTM is an antibody directed against the α subunit of the interleukin 4 receptor (IL-4R-α), and the TezsipreTM blocks thymic stromal lymphopoietin (TSLP), which plays a key role in asthma." (PMID 36140426, 2022). "In patients with mild to moderate asthma, basophils were strongly activated by TSLP leading to secondary production of IL-3, suggesting that in certain contexts TSLP and IL-3 can also act in concert." (PMID 36846020, 2022). "With TSLP inhibition, type 2 inflammation decreases, the asthma exacerbation rate is significantly reduced and clinical symptoms are improved." (PMID 36355519, 2022). "In contrast, little is known about the clinical relevance of TSLP secretion in the lower airways of children with asthma." (PMID 36245744, 2022). "TSLP expression in asthma patients correlates with both airway obstruction and the severity of the disease." (PMID 35572064, 2022). "RV infection has been suggested to be associated with the development of asthma, and RV16 infection upregulates TSLP and IL-33 expression in human lung epithelial cells." (PMID 35292112, 2022). "The wide distribution of TSLPR expression indicates the potency of TSLP to induce broad effects throughout the body, although much remains to be elucidated regarding the role of TSLP in airway inflammation and asthma." (PMID 36311787, 2022). "NET components, such as high-mobility group box 1 protein (HMBG1), can activate BECs to release several mediators involved in asthma pathogenesis, including TSLP, TNF-α, MMP-9, and VEGF." (PMID 36359917, 2022). "Given that pediatric asthma is major health problem worldwide, we feel larger longitudinal studies are urgently needed to define additional features of TSLP production in the lungs of asthmatic children." (PMID 36245744, 2022). "Tezepelumab, the first-in-class anti-TSLP monoclonal antibody, was approved as a biological agent for the treatment of severe asthma." (PMID 36046760, 2022).